GNRHR2 (gonadotropin releasing hormone receptor 2 (pseudogene) )
Synonyms: GNRHR2P; GnRH-II-R
Gene: Long non-coding RNA gene on chromosome 1 (145,919,013 to 145,925,341, forward strand). Ensembl gene ENSG00000293505.
Diseases named in the same sentence as GNRHR2 in open-access papers:
GNRHR2 is named in the same sentence as 7 diseases in open-access papers, as found by Europe PMC text mining. Sharing a sentence is not in itself a finding about the gene and the disease. The quoted sentences say what the papers report.
ovarian carcinoma (2 papers, 2017 to 2023). A malignant neoplasm originating from the surface ovarian epithelium. "Treatment with several GnRHR2 antagonists inhibited growth of human endometrial and ovarian cancer cells in vitro and in vivo via caspase 3-dependent mechanisms; a different GnRHR2 antagonist (SN09-2) induced apoptosis in prostate cancer cells." (PMID 29312140, 2017). "Together, these findings suggest that GnRHR2 is functional in certain ovarian cancer cells." (PMID 38260130, 2023). "However, GnRH2 was the most potent competitor, indicating the presence of a functional 5-TM GnRHR2 in human ovarian cancer cells." (PMID 38260130, 2023). "Both immunoblotting of protein and photo labeling studies of cell membrane fractions from ovarian cancer cells (EFO-21, SK-OV-3) resulted in a band corresponding to the 5-TM GnRHR2 isoform (43-kDa)." (PMID 38260130, 2023). "GnRHR1 mRNA was downregulated by FSH or LH in most ovarian cancer cell lines but GnRHR2 expression was not examined." (PMID 38260130, 2023). "In SK-OV-3 ovarian cancer cells (expressing GnRHR2 but not GnRHR1), GnRH2 exhibited powerful anti-proliferative effects, unlike triptorelin, suggesting that GnRHR2 is mediating these effects." (PMID 38260130, 2023).
prostate carcinoma (2 papers, 2017 to 2023). A carcinoma that arises from epithelial cells of the prostate gland. "Photoaffinity labeling suggested that GnRH2 binds with high affinity to a protein in prostate cancer cells, implicating GnRHR2." (PMID 38260130, 2023). "Human prostate cancer cells treated with a GnRHR2 antagonist (Trptorelix-1) displayed increased mitochondrial dysfunction as well as autophagosome formation." (PMID 29312140, 2017). "Therefore, GnRH2 and GnRHR2 may be involved in autocrine/paracrine regulation of prostate cancer progression." (PMID 38260130, 2023).
cervical cancer (1 paper, 2023). A primary or metastatic malignant neoplasm involving the cervix. "There is a critical need to better understand the potential function of GnRH2 and GnRHR2 in these cells since cervical cancer is the second most common cancer in women." (PMID 38260130, 2023).
endometrial carcinoma (1 paper, 2023). A malignant tumor arising from the epithelium that lines the cavity of the uterine body. "Co-expression of GnRH2 and GnRHR2 suggest an autocrine/paracrine role in endometrial cancers." (PMID 38260130, 2023). "Indeed, both low and high affinity binding sites for GnRH1 were detectable in human endometrial cancer cells, implicating the presence of GnRHR1 (high) and GnRHR2 (low)." (PMID 38260130, 2023). "Triptorelin, cetrorelix (pan GnRHR antagonist), and GnRH2 exerted anti-proliferative effects on endometrial cancer cells (Ishikawa, HEC-1A, and HEC-1B) that produce GnRHR1 and GnRHR2 transcripts." (PMID 38260130, 2023).
testicular cancer (1 paper, 2023). A primary or metastatic malignant neoplasm that affects the testis. "Although GnRH2 and GnRHR2 have been investigated in the regulation of many different reproductive cancers, there is a gap in our knowledge regarding the potential influence of GnRH2 and GnRHR2 as a therapeutic to treat testicular cancer." (PMID 38260130, 2023).
cancer (2 papers, 2017 to 2023). A tumor composed of atypical neoplastic, often pleomorphic cells that invade other tissues. "Recently, GnRH2 and GnRHR2 have been detected in reproductive cancer cells." (PMID 38260130, 2023). "Indeed, many independent groups have reported evidence for a functional GnRHR2 in reproductive cancer cells." (PMID 38260130, 2023). "However, GnRH2 and/or GnRHR2 are also expressed in other reproductive cancer cells (cervical, placenta), warranting further study." (PMID 38260130, 2023). "Furthermore, both the GnRH2 and GnRHR2 genes are expressed in human reproductive tumors and represent emerging targets for cancer treatment." (PMID 29312140, 2017). "Furthermore, both GnRH2 and GnRHR2 are expressed in human reproductive tumors and are emerging targets for cancer treatment." (PMID 29312140, 2017). "Thus, GnRH2 and GnRHR2 may be novel, unexploited cancer targets." (PMID 38260130, 2023).
GNRHR2 also shares sentences with these, for which no sentence is quoted: reproductive tumors (1 paper).